CD4 (CD4 molecule)
Diseases named in the same sentence as CD4 in open-access papers (continued):
Sharing a sentence is not in itself a finding about the gene and the disease.
tumor (continued). "The exhausted CD8+ T-cell phenotype has been associated with an increased risk of tumor progression, increased dysfunctional dendritic cells (DCs), and elevated numbers of immune cells, namely M2-polarized macrophages, resting mast cells, resting memory CD4+ T cells, and CD4+ Foxp3+ Tregs." (PMID 34208157, 2021). "Based on data of TIMER immune-gene database which collects immunocytes’ infiltration score of TCGA tumor samples, we further investigated the correlation between risk score and immunocyte infiltration, including neutrophils, dendritic cells (DC), macrophages, CD4+T cells, and CD8+T cells." (PMID 34858419, 2021). "Finally, reduced CD3 + (p = 0.04, rho = 0.60) and CD4 + (p = 0.01, rho = 0.72) T-cell counts in 'On-treatment' biopsies were associated with decreased residual tumour content post-1 cycle of treatment; the latter being significantly associated with increased likelihood of subsequent pCR (p < 0.01)." (PMID 33983492, 2021). "Our study identified differences in tumor infiltrating cells between high-risk and low-risk groups according to an immune-related lncRNA model, focusing on cells including dendritic cells, B cells, CD4 T cells, CD8 T cells, Natural killer cells, T follicular helper cells, and mast cells." (PMID 34745939, 2021). "We speculate that the absence of this pretreatment immunosuppression in responders promotes the 1) advantageous spatial interactions of tumor and PD-1+ CD4+ T cells that underlies the lower SpatialScore and 2) priming and activation of CD4+ T cells following immunotherapy." (PMID 34795254, 2021). "Several immune cells, such as myeloid-derived suppressor cells (MDSCs), tumor-associated macrophages (TAMs), Tregs and immature DCs, all play a central role in tumor growth and metastasis and by accumulating in LNs can inhibit the anti-tumor immune activities of CD4, CD8 T cells and NK cells." (PMID 34241649, 2021). "plasma cells, T cells CD8, T cells CD4 memory activated, and T cells follicular helper were reported to play important roles in inhibiting tumors, while macrophages and mast cells activated have been proved to be associated with tumor metastasis and poor prognosis." (PMID 34322156, 2021). "Also of interest are inhibitory receptors that may be engaged by tumor- or tumor stromal-associated ligands, and therefore act as additional “checkpoints” to inhibit cytotoxic CD4+ T cell activity." (PMID 34910940, 2021). "Therefore, the artificial elongation of tumor-associated CD8+ Tcell epitopes or the application of multivalent long peptides comprising at the same time CD4+ and CD8+ T cell epitopes displays promising attempts to improve the efficacy and clinical outcome of peptide vaccination." (PMID 33583769, 2021). "Indeed, IL4 produced by TGF-β receptor 2 (TGFBR2)-deficient CD4+ T cells in a mouse model of breast cancer could reprogram the tumor vasculature and triggered cancer cell hypoxia and death." (PMID 34262562, 2021). "Additionally, not only CD8+ but also CD4+ lymphocytes have been implicated in tumor control." (PMID 34445713, 2021). "Interestingly, we observed a significant increase in CTLA-4 expression in CD4+ T cells co-cultured with STING deficient tumor cells compared to WT, which may be due to alternative compensatory pathways." (PMID 33995649, 2021). "Furthermore, tumor cell-extrinsic STAT3 activation also regulates the immune tolerance and suppression of anti-tumor immunity by upregulating the expression of immune checkpoint proteins (e.g., PD1, CTLA4) on the surface of tumor-associated myeloid cells, B-cells, Tregs, and CD4 and CD8 T-cells." (PMID 34944848, 2021). "Moreover, we found that CD8+ T cell and activated CD4+ memory T cell tumor infiltration was lower in the high-risk group, while high-risk score correlated positively with higher tumor mutational burden, and the higher half inhibitory centration 50 of chemotherapeutic agents Docetaxel and Sunitinib." (PMID 34654352, 2021).
tumor (continued). "Furthermore, MUC4 mutant samples presented a higher infiltration proportion of follicular helper T cells and activated memory CD4 T cells, which is in line with previous established evidence that anti-tumor immune response was associated with these immune cells and pathways." (PMID 33714943, 2021). "In our study, six tumor-infiltrating immune cell subtypes were found to be present in different frequencies between the high- and low-risk subgroups, and the risk score was moderately correlated with the CD4+T cells and weakly associated with five other tumor-infiltrating immune cell subtupes." (PMID 33194633, 2020). "Hence, to determine whether the early T cell response induced by Ubr5 deletion was responsible for the observed tumor diminution, we compared tumor growth in Rag2−/− mice, CD4-deficient mice and CD8-deficient mice." (PMID 33293516, 2020). "Moreover, tumour‐infiltrating PTPN2‐deficient CD4+ and CD8+ effector/memory T cells were significantly more active, as assessed by the PMA/ionomycin‐induced production of markers of T‐cell cytotoxicity ex vivo, including interferon (IFN)‐γ and tumour necrosis factor (TNF)." (PMID 31803974, 2020). "Combined, these findings suggest that MIF promotes tumor-associated immune evasion by inhibiting DC infiltration, maturation, and antigen presentation; all of which are inherently required for the development of anti-tumor CD4+ and CD8+ T cell effector functions." (PMID 33324425, 2020). "Interestingly, tumor cells expressed Ltbr, which encodes a receptor for Lta and Ltb that were expressed by late ductal cells and by several immune cell-types, including CD4 T cells from the 15 months PTI sample." (PMID 32908137, 2020). "Additionally, MCPyV TAg-specific cells gated on CD3+CD4+TNFα+ cells were polyfunctional for IL-2 and the Th1 effector molecules granzyme B, IFNγ, and TNFα, a feature associated with immune-mediated tumor clearance." (PMID 33362774, 2020). "Although the high density of TILs (Tumor-Infiltrating Lymphocytes) is normally associated with a response of the host immune system against cancer and better outcome, this cellular response can be dysfunctional with a higher proportion of CD4+ (helper or T regulatory cells) to CD8+ cells." (PMID 32164265, 2020). "Tumor-associated conventional DCs (cDCs) are considered to phagocytose debris from apoptotic cancer cells and transport cancer-related antigens to the draining lymph node where these antigens are presented to naïve CD4+ or CD8+ T cells and induce T cell priming and activation." (PMID 33148302, 2020). "Large solid tumors can evade anti-tumor immunity partly by inducing an immunosuppressive/tolerogenic microenvironment that includes regulatory cells such as myeloid-derived suppressor cells (MDSCs), tumor-associated macrophages (TAMs), and regulatory CD4+ T-cells (Tregs)." (PMID 30873170, 2019). "Therefore, both direct presentation by cancer cells and indirect cross-presentation of tumor-derived NUP214 by hematopoietic antigen-presenting cells are possible as a mechanism for activation of mutated NUP214-specific CD4+ T-cells in the tumor microenvironment." (PMID 31221207, 2019). "Among TILs, we noted that ~87% of GP66-specific CD4+ T cells expressed programmed cell death 1 (PD-1), encoded by Pdcd1 and a marker of antigenic stimulation, suggesting that it could serve as an indicator of tumor specificity." (PMID 31801070, 2019). "However, tumors are often infiltrated by inhibitory immune cells such as myeloid derived suppressor cells (MDSCs) or tumor associated macrophages (TAMs) acting in concert with regulatory CD4+ T cells to create an immunosuppressive microenvironment that becomes hostile to activated T effector cells." (PMID 30853959, 2019).
tumor (continued). "Finally, a metastatic cholangiocarcinoma patient experienced disease regression and stabilization after therapeutic administration of T cell products generated from neoantigen-reactive CD4+ T cells that recognized one neoantigen out of 26 transcribed mutations detected in the tumor tissue." (PMID 31888734, 2019). "Thus, future studies must be conducted to evaluate the effect of diet and exercise on specific T-cell types affecting tumor progression, because tumor growth is directly modulated by the function of CD4+ cells controlling tumor tolerance and by inflammatory cells augmenting tumor growth." (PMID 31528182, 2019). "Indeed, IL-12 was proposed for the treatment of certain cancers in which Tregs and TGF-β play a role in suppressing the activity of tumor-associated CD4+ and CD8+ T cells, but the systemic administration of soluble IL-12 in effective doses is dangerously toxic." (PMID 29404418, 2018). "For example, cytotoxic CD8+ T cells, memory T cells, and CD4+ T helper cells are generally associated with a better prognosis, whereas T regulatory cells, tumor associated macrophages, and myeloid-derived suppressor cells are associated with poor prognosis and can promote tumor progression." (PMID 30211161, 2018). "The recent data demonstrating that vaccines constituted by mutation-derived CD4+/CD8+ T cell neoepitopes induce anti-tumor immune responses in both preclinical and clinical settings, had prompted us to test whether the unique properties of OMVs could be exploited in cancer immunotherapy." (PMID 30416985, 2018). "Based on our observation of a consistent increase in local and systemic IL-10 concentrations, associated with elevated numbers of CD4+ T cells in the lungs of metformin-treated tumor-bearing mice, we subsequently assessed whether Treg cells could be induced in this context." (PMID 29899823, 2018). "Although the ideal CAR target is expressed on 100% of tumor cells with 100% specificity, tumor-associated antigens are usually expressed on only a subset of cancer cells, unless the normal cells from which the tumor is derived also share that antigen, as is the case with CD4." (PMID 29348865, 2017). "Recently, CD8+ T cell survival and anti-tumor activity in vivo were shown to be enhanced by increased intracellular l-arginine levels, suggesting the reduction in CD4+ T cell accumulation in the mLN and lungs of Asl-deficient mice may be tied to decreased survival." (PMID 29201027, 2017). "Furthermore, inhibition of CD4+ Foxp3+ Treg cells could be another mechanism associated with enhanced NK cell immunity in the tumour-bearing Smad3−/− mice." (PMID 28262747, 2017). "Hence, it is likely that anti-tumour responses in treated mice are linked to the accumulated CD11b+ DCs that could activate CD4 T cells to produce IL-2, necessary for the efficient generation of CD8 effector T cells." (PMID 27341421, 2016). "Moreover, the decreasing ratio of CD4+/CD8+ was associated with tumor progression." (PMID 27800005, 2016). "Therefore, whether the changes in CD4+ T-cell subsets in RCC patients are the cause of tumorigenesis or the consequence of tumor development requires further investigation." (PMID 25352158, 2015). "Solitomab, compared to control BiTE®, caused an increase in the production of type 1 cytokines and cytotoxic activity of tumor associated lymphocytes isolated from pleural fluid in CS harboring patients and may increase recruitment as well as activation of CD4 and CD8+ T cells." (PMID 26474755, 2015). "Similarly, another report showed that L-selectinlow CD4 cells caused tumor regression." (PMID 26090481, 2015). "Similarly, treatment of a patient with metastatic melanoma with autologous CD4+ T cells specific for the tumor-associated antigen NY-ESO-1 resulted in sustained clinical remissions with evidence of endogenous immune responses against other tumor-derived antigens." (PMID 24782871, 2014).
tumor (continued). "Importantly, the in vivo anti-tumor effects of IT also remained intact in CD4+ deficient models." (PMID 25119341, 2014). "Finally, we investigated the association of CD4+Foxp3+LAP+ T cells with tumor stage." (PMID 25268580, 2014). "Indeed, infiltration with CD8+ T cells and a higher ratio of CD8+ to CD4+ T cell in tumor are associated with an improved outcome and decreased metastasis in multiple cancer lineages indicating that infiltrating immune cells can have anti-tumor activity." (PMID 25520884, 2013). "However, the role of Th2 effector cells in the antitumor immune response remains unclear with several studies suggesting that such CD4 effector cells are associated with carcinogenesis and tumor progression." (PMID 23533029, 2013). "The relevance of CD4+ Tregs in suppressing the anti-tumor immune response is well documented, and numerous studies have reported that the accumulation of Tregs in cancer patients is generally associated with tumor progression, a poor prognosis and the suppression of anti-tumor immunity." (PMID 23589107, 2013). "Interestingly, the frequencies of CD4+Nrp1+CD25high T cells were reduced in the tumor-draining lymph nodes of cervical cancer patients after chemoradiation therapy, which was associated with a decrease in the tumor mass." (PMID 24324469, 2013). "In parallel to a reduction in tumor growth, we observed in IL-10 deficient mice or mice treated with anti-IL-10/anti-IL-10R neutralizing antibodies that there was an increase tumor infiltration by CD4 and CD8 lymphocytes, which were rare in tumors from control wild type mice." (PMID 20525400, 2010). "Thus, γc down regulation and inhibition of Jak-3/Stat-5A signaling by PGE2 present in the tumor supernatant, as obtained here, may fail to support sustained Bcl-2 expression, leading to CD4+ T cells susceptibility towards apoptotic death." (PMID 19812686, 2009). "Biologically, we re-define the Tfh-like compartment not merely as B-cell helpers, but as a critical progenitor reservoir for CD4+ effector populations within the tumor." (PMID 41542042, 2026). "Additional analysis uncovered distinct categories within tumor-associated macrophages (TAMs), CD8+ T cells, and CD4+ T cells." (PMID 41635288, 2026). "Functional assays confirmed that miR‐19a‐3p enhances CD4+ T cell cytotoxicity and counteracts HBx‐driven lymphomagenesis, establishing a mechanistic connection between viral regulation and anti‐tumour immunity." (PMID 41492119, 2026). "Sustained IFN-β secretion subsequently inhibits NSCLC cell proliferation and reprograms the tumor microenvironment by increasing the infiltration levels of CD4+ T cells, M1 macrophages and NK cells." (PMID 41545343, 2026). "CD38 + NK cells from tumor patients can stimulate CD4 + T cells to differentiate into Tregs and macrophages to polarize into M2 type, which constitutes an immune microenvironment conducive to the growth of tumor cells." (PMID 41530841, 2026). "To better understand the role of CD4+ T cells in anti-tumour immunity, we analysed the HLA-II immunopeptidome of dendritic cells (DCs) from HLA-heterozygous donors pulsed with a protein extract from the MCF-7 tumour cell line." (PMID 41607090, 2026). "Previous studies have suggested that the prolonged functionality of primary CD4+ T cells in tumor settings is partly due to their ability to maintain a less differentiated, memory-like state and resist exhaustion." (PMID 41484912, 2026). "Immune reaction of CD4+ T cells modulate the tumor microenvironment (TME) through cytokine secretion or co-stimulation signals and help CD8+ T cell priming through modulating dendritic cells (DCs)." (PMID 41348109, 2026). "This significantly promoted the infiltration of CD8+ and CD4+ T-cells (by 3.95-fold and 3-fold, respectively), successfully converting a "cold tumor" into an immunogenic "hot tumor"." (PMID 41510161, 2026).
tumor (continued). "Specifically, C1-GBM was categorized as an immune-infiltrated “hot” tumor, with high infiltration of immune cells, particularly macrophages and CD4+ T cells, while C2-GBM as an “inherent driving” subtype, showing elevated activity in G2/M checkpoint genes." (PMID 41614933, 2026). "This crucial involvement of CD4+ T cells in initiating and sustaining an anti-tumour immune response supports the idea that they have potential to be a good predictor of outcome and/or indicator of response to immunotherapy." (PMID 41574275, 2026). "The drug products comprise mutant-reactive, polyfunctional, and cytotoxic CD8+ and CD4+ T cells, able to recognize autologous tumor material." (PMID 41644530, 2026). "High CLK1 expression correlated with prolonged survival, suppressed cell cycle and metabolism pathways, and enhanced anti-tumor immunity-particularly CD4+ T cell infiltration." (PMID 41737282, 2026). "After being cultured with UBSC039-pretreated tumor cells, the percentage of Tregs among CD4 + T cells was elevated significantly." (PMID 41530841, 2026). "Blocking antibodies against PD-1/PD-L1 have demonstrated the potential to activate tumor-specific immune cells, particularly CD4+ and CD8+ T cells." (PMID 41675286, 2026). "CD4+ T cell activation in the spleen was directly linked to increased IFN-γ and TNF-α production by CD8+ T cells within the tumor microenvironment, fostering a reduction in Tregs and mitigating local immunosuppression." (PMID 41522339, 2026). "Accumulation of Tregs, a subset of CD4+ T cells, within the tumour microenvironment decreases the function of effector T cells, and prevents effective anti-tumour T cell responses." (PMID 41476776, 2026). "The presentation of antigens by HSPCs to CD4+ T cells biased HSPC lineages toward myelopoiesis and polarized CD4+ T cells to regulatory T cells, culminating in tumor immunotolerance." (PMID 41634415, 2026). "To systematically characterize the tumour cell‐CD4+ T cell communication network, we performed ligand–receptor (L‐R) pair analysis leveraging single‐cell transcriptomic profiles from 4 DLBCL cases." (PMID 41492119, 2026). "Functional perturbations revealed that retinoid signaling partially contributes to, whereas CD4+ T cells are essential for, tumor control." (PMID 41817619, 2026). "HBx overexpression markedly decreased tumour‐infiltrating CD4+ T cells, whereas miR‐19a‐3p agomir restored their infiltration." (PMID 41492119, 2026). "Intriguingly, infusion of these CD44low CD4 + T cells attenuated body weight reduction and preserved skeletal muscle mass in tumor-bearing mice." (PMID 41526343, 2026). "Although depletion of CD4+ T cells suppressed overall tumor volume, possibly through depletion of regulatory T cells (Tregs), CD4 depletion abrogated antitumor activity of CTA." (PMID 41348109, 2026). "IPI-549 or PD-L1 single or dual treatments did not affect PD-1, CTLA-4, TIGIT, LAG-3, or TIM-3 expression in tumor-infiltrating CD4+ T-cells in HNSCC tumor-bearing mice." (PMID 41431358, 2026). "To determine the activation states of tumor-infiltrating T cells, we examined the expression of exhaustion markers on tumor-infiltrating CD4+ and CD8+ T cells." (PMID 41431358, 2026). "Tissue-resident memory CD4+ T cells (CD4+ TRMs) are pivotal in immune responses during inflammation and infection, yet their phenotype and function within the tumor microenvironment (TME) remain elusive." (PMID 41486351, 2026). "As seen in the other animal groups, the majority of leukocytes in the tumor were represented by CD4+ T‐lymphocytes." (PMID 41522488, 2026). "After removing residual UBCS039 from the cells, we cultivated these tumor cells in a transwell system with human naive CD4 + T cells to monitor T-cell differentiation." (PMID 41530841, 2026).